TYRP1 (tyrosinase related protein 1)
Description:
Plays a role in melanin biosynthesis. Catalyzes the oxidation of 5,6-dihydroxyindole-2-carboxylic acid (DHICA) into indole-5,6-quinone-2-carboxylic acid in the presence of bound Cu(2+) ions, but not in the presence of Zn(2+). May regulate or influence the type of melanin synthesized. Also to a lower extent, capable of hydroxylating tyrosine and producing melanin (By similarity).
Synonyms: TRP; TRP1; CAS2; TYRP; GP75; CATB; b-PROTEIN; OCA3
Tractability: Small molecule: a structure with a bound ligand is known; it belongs to a druggable protein family. Antibody: a drug acting on it is in phase 2 or 3 trials; UniProt predicts a signal peptide or a membrane-spanning region.
Target class: Enzyme; Oxidoreductase
Gene: Protein-coding gene on chromosome 9 (12,685,439 to 12,710,285, forward strand). Ensembl gene ENSG00000107165.
Subcellular location: Melanosome membrane
Subcellular location (Human Protein Atlas): Vesicles
Pathways (Reactome):
Developmental Biology: Regulation of MITF-M-dependent genes involved in pigmentation
Metabolism: Melanin biosynthesis
Gene Ontology:
Molecular function: protein binding; tyrosinase activity; catechol oxidase activity; protein homodimerization activity; identical protein binding; oxidoreductase activity
Biological process: positive regulation of melanin biosynthetic process; melanin biosynthetic process; melanocyte differentiation; melanosome organization; eye development; eye pigmentation
Cellular component: clathrin-coated endocytic vesicle membrane; cytoplasm; endosome membrane; intracellular vesicle; melanosome; melanosome membrane; bounding membrane of organelle; cytoplasmic vesicle membrane
Genetic constraint (gnomAD): Loss-of-function variants: 55 observed, 49.25 expected, observed/expected ratio (o/e) 1.12, 90% interval 0.9 to 1.4. The upper end of that interval is the gene's LOEUF score, 1.4, which puts it in group 5 of 6, group 1 being the genes least tolerant of losing a copy. Missense variants: 848 observed, 697.23 expected, observed/expected ratio (o/e) 1.22, 90% interval 1.15 to 1.29. Synonymous variants: 279 observed, 248.47 expected, observed/expected ratio (o/e) 1.12, 90% interval 1.02 to 1.24.
Homologues: Orthologues: chimpanzee TYRP1 (99% identical), macaque TYRP1 (97% identical), pig TYRP1 (90% identical), rabbit TYRP1 (90% identical), mouse Tyrp1 (85% identical), rat Tyrp1 (85% identical), guinea pig TYRP1 (78% identical), tropical clawed frog tyrp1 (69% identical), zebrafish tyrp1b (66% identical), zebrafish tyrp1a (66% identical), Caenorhabditis elegans tyr-4 (17% identical), Caenorhabditis elegans F54E4.4 (7% identical). Paralogues in human: DCT (47% identical), TYR (38% identical).
Diseases named in the same sentence as TYRP1 in open-access papers:
TYRP1 is named in the same sentence as 136 diseases in open-access papers, as found by Europe PMC text mining. Sharing a sentence is not in itself a finding about the gene and the disease. The quoted sentences say what the papers report.
melanoma (208 papers, 2006 to 2025). A malignant, usually aggressive tumor composed of atypical, neoplastic melanocytes. "In follow-up studies, a vaccine using the tumor-associated antigen tyrosinase-related protein 1 (TRP1) provided increased protection in the mouse melanoma model." (PMID 40657919, 2025). "With respect to TYRP1 variants (rs281865424–p.R356E and rs1408799), rs1408799 was identified as a melanoma risk factor under the log-additive model (OR = 2.29, CI = 1.07–4.90, p = 0.027)." (PMID 40429816, 2025). "Another area of interest is surface-expressed tyrosinase-related protein 1 (TYRP1), a melanosome-associated protein trafficked to the plasma membrane in cutaneous and rare melanoma subtypes." (PMID 40940995, 2025). "The VSV-hIFNβ-TYRP1 variant has been used in clinical trials as anagent against stage III/IV melanoma." (PMID 39877014, 2024). "Conversely, the melanoma associated genes gp100 or TYRP1 were abundant in the ASMEL library but were essentially undetectable in the VSV-IFNß-SB-HCC 1,2,3 cDNA library." (PMID 38045348, 2023). "Interferon gamma (IFNγ) ELIspot data showed that more patients developed a T cell response to virus encoded TYRP1 at higher DLs, and a subset of patients also had a response to other melanoma antigens, including gp100, suggesting epitope spreading." (PMID 38022659, 2023). "We examined how ZNT5–6 and ZNT7 are associated with the expression of TYRP1 in another human melanoma cell line, SK-MEL-2, which is deficient in both ZNT5 and ZNT7 (SK-Z5Z7-DKO), because of their usefulness in transient transfection studies." (PMID 37072620, 2023). "The microarray analysis of melanoma metastasis conducted by Journe found that the gene TYRP1 was associated with shorter survival." (PMID 36614156, 2022). "It has been shown that different combinations of AA/CC alleles of rs683/rs910 SNPs that lie in the 3′UTR region of TYRP1 mRNA affect the expression of TYRP1 at a post-transcriptional level while there is also a correlation with melanoma metastasis." (PMID 34449663, 2021). "The low-risk melanoma gene group revealed 12 carriers of mutations in 5 genes (another TYRP1 carrier also had a pathogenic BRCA2 mutation)." (PMID 33050356, 2020). "In another study, 17-AAG increased expression of DCT (dopachrome tautomerase) and TYRP1 (tyrosinase-related protein 1) encoding pigmentation-related proteins, and elevated melanin production in melanoma cells." (PMID 31659567, 2020). "In animal models, immunization against melanoma as well as treatment with a monoclonal antibody against tyrosinase-related protein-1 (TRP-1/gp75) can cause melanoma-associated leukoderma." (PMID 31731645, 2019). "Adoptive transfer of Tyrp1-specific CD4+ T cells by itself caused significant regression of established tumor relative to vehicle treated melanoma bearing mice." (PMID 29481571, 2018). "In two models, these antigens are bona fide cancer antigens; the tumor-specific myeloma protein V region idiotype (Id) and the melanoma-associated tyrosinase-related protein 1 (Trp1)." (PMID 24782871, 2014). "Among the genes found to be downregulated in the UVM subtracted library, several were previously associated with melanoma, such as melanocytic markers TYRP1, EDNRB, MTAP, and sex determining region Y box 4 (SOX4)." (PMID 21647268, 2011). "In C57BL/6 mice, the growth of the melanoma B16 is inhibited by treatment of the mice with the mouse IgG2a monoclonal antibody TA99 anti-Tyrosinase Associated Protein TYRP-1/gp75." (PMID 20672001, 2010). "Genetic analyses further support shared susceptibility, as pigmentation-related variants near ASIP (encoding agouti signaling protein), TYR (encoding tyrosinase), and TYRP1 (encoding tyrosinase-related protein 1) were associated with both melanoma and BCC in European populations." (PMID 41374951, 2025). "TYRP1 was mutated in 10 melanomas, 8 acral and 2 mucosal melanomas." (PMID 35706047, 2022).
melanoma (continued). "Interestingly, TYRP1 mRNA levels in cells carrying mutation either in NRAS or in HRAS were much higher than in BRAFV600E melanoma cells." (PMID 31624899, 2020). "Interestingly, in the recent TCGA study another gene involved in melanogenesis and increased risk of melanoma that is the TYRP1 locus has been selected as differentially expressed in ccRCC." (PMID 25945350, 2015). "Many pigmentation genes linked to melanoma in recent GWAS such as TPCN2, ASIP, KIT, NCKX5, TYR, IRF 4, OCA2 and TYRP1 have been linked to melanoma and some of them like MC1R have dual roles in pigmentation and immune responses but many other functions of these genes remain to be discovered." (PMID 23796690, 2013). "To demonstrate our approach, we used TRP1high TCR transnuclear mice as a source of CD8 T cells that recognize a well-described melanoma antigen, tyrosinase-related protein 1 (TRP1), with physiological pMHC:TCR affinity." (PMID 41202121, 2025). "In a preclinical study, investigators at UCLA generated CAR T-cells targeting TYRP1, a protein abundantly present in melanoma cells." (PMID 40004731, 2025). "Based on safety and efficacy observed in preclinical models, the authors are preparing to initiate a first-in-human Phase I trial targeting TYRP1 in melanoma." (PMID 40940995, 2025). "The first panel highlights melanoma-associated genes, including MITF, AXL, NGFR, TYRP1, and DCT, which are involved in the regulation of melanoma cell identity, dedifferentiation, and invasive potential." (PMID 40909289, 2025). "In an open-label, dose-escalation phase I study, 27 patients with advanced melanoma (who had progressed on or during at least 1 prior therapy) received intravenous IMC-20D7S (a recombinant human IgG1 monoclonal antibody targeting TYRP1) every 2 or 3 weeks." (PMID 40988203, 2025). "The research team has highlighted the significant TYRP1 overexpression in cancer cells and demonstrated remarkable efficacy both in vitro and in-vivo murine/patient-derived melanoma models." (PMID 40040721, 2025). "TCR-transgenic Trp1 CD4+ T cells recognize the melanoma antigen tyrosinase-related protein 1 (Trp1)." (PMID 40634636, 2025). "TYRP1 is a target for CAR-T cell therapy in melanoma subtypes unresponsive to immune checkpoint blockade." (PMID 40809015, 2025). "Currently, an active clinical trial (NCT03865212) is evaluating a recombinant vesicular stomatitis virus (VSV) platform expressing IFNβ and tyrosinase-related protein 1 (TYRP1), a melanoma-specific antigen." (PMID 40725830, 2025). "TYRP1 was highly overexpressed (log2 FPKM ≥ 7) in ~30% of melanomas overall and up to ~90% in uveal melanoma, including in biopsies from patients resistant to immune checkpoint inhibitors, supporting its clinical relevance." (PMID 40940995, 2025). "As a result of PACAP administration, the TYRP1 expression was reduced, demonstrating the complexity of the role of this neuropeptide in melanoma behaviour." (PMID 41465475, 2025). "Many well-known pigmentation genes were among the 150 most upregulated genes in the intradermal melanomas: Slc45a2, Tyrp1, Tyr, Pmel, Dct, Oca2, Mlana, Slc24a4, and Mc1r." (PMID 39804140, 2025). "Variants in TYR, TYRP1, CDKN2A, and HERC2 significantly contributed to risk, and light brown eye and hair colors were strongly associated with increased melanoma risk." (PMID 40429816, 2025). "TYRP1 is often expressed in melanoma and its increased levels have been found in some metastatic tumours." (PMID 41465475, 2025). "The TYRP1 CAR-T cell therapy we have developed is exclusively designed to treat patients with melanoma." (PMID 38336975, 2024). "Twenty participants with cutaneous, uveal, or mucosal TYRP1-positive melanoma received TYRP1-TCB in escalating doses (0.045 to 0.4 mg)." (PMID 38577337, 2024). "In cell culture and mouse tumor models, simultaneous binding to both targets leads to T−cell activation and concomitant T−cell mediated killing of TYRP1-positive melanoma cells." (PMID 38577337, 2024).
melanoma (continued). "Altogether, these results highlight the clinical relevance of TYRP1 as a target for melanoma therapies and demonstrate the feasibility of targeting the surface expression of TYRP1 with CAR-T cell therapy." (PMID 38336975, 2024). "Similar to the results observed in melanoma lesions, 27 of these cell lines expressed TYRP1 (Log2 FPKM ≥ 1), and 15 of them presented a high overexpression (Log2 FPKM ≥ 7)." (PMID 38336975, 2024). "TYRP1 is a transmembrane glycoprotein that is specifically expressed in melanocytes and melanoma cells." (PMID 39943991, 2024). "Due to the lack of cross-reactivity of the hRS7-derived scFv with mouse TROP2, we established a B16/F10-OVA mouse melanoma model that expresses the gp75 (also known as tyrosinase-related protein-1 or TRP-1) antigen." (PMID 39735543, 2024). "In conclusion, the VIBE analysis conducted on the GSE91061 and TCGA datasets suggests that TYRP1 holds potential as a therapeutic target for melanoma." (PMID 39943991, 2024). "TYRP1-TCB (RO7293583; RG6232) is a T-cell engaging bispecific (TCB) antibody that targets tyrosinase-related protein 1 (TYRP1), which is expressed in many melanomas, thereby directing T cells to kill TYRP1-expressing tumor cells." (PMID 38577337, 2024). "This trial demonstrates the safety and feasibility of targeting TYRP1 surface expression in patients with melanoma and highlights the need to identify strategies to increase the overall antitumor activity." (PMID 38336975, 2024). "Since the TYRP1 CAR-T cells target only melanoma cells with high levels of TYRP1 expression, our scoring method will only consider the percentage of cells with a 3+ intensity stain." (PMID 38336975, 2024). "Next, we measured the cytotoxicity and cytokine release of the 20D7S-derived CARs when co-cultured with a panel of patient-derived melanoma cell lines with high (M285, M249, M230, and M207) and intermediate (M202 and M229) total TYRP1 expression." (PMID 38336975, 2024). "We validated the staining with a TYRP1-specific antibody and used the 38 patient samples from metastatic melanoma lesions to develop a scoring system that will be used as an inclusion-exclusion criterion to enroll patients in the phase I clinical trial." (PMID 38336975, 2024). "According to recent studies, MITF is required for melanin synthesis, but MITF is unable to induce the expression of tyrosinase and TYRP1 in B16 mouse melanoma cells or human melanocytes." (PMID 38711645, 2024). "TRP1 also can regulate melanocyte proliferation and prevent cell death with non-coding TYRP1 mRNA promoting melanoma growth." (PMID 38927967, 2024). "20D7SL CAR’s cross-reactivity against human and murine TYRP1 allows us to evaluate toxicity in the syngeneic B16 melanoma model in immunocompetent C57BL/6 mice subjected to lymphodepleting total body irradiation one day prior to CAR-T cell administration." (PMID 38336975, 2024). "TRAEs observed with TYRP1-TCB in participants with TYRP1-positive melanoma were consistent with its expected mechanism of action and were generally manageable across the tested dose range of 0.045 to 0.4 mg." (PMID 38577337, 2024). "Loss of ZNT5–6 and ZNT7 function results in hypopigmentation in medaka fish and human melanoma cells, and is accompanied by immature melanosomes and reduced melanin content, as observed in TYRP1 dysfunction." (PMID 37072620, 2023). "We use TRP1high and TRP1low transnuclear mice bearing CD8 T cells that recognize an epitope from the melanoma self-antigen tyrosinase-related protein 1 (Tyrp1) with different affinities." (PMID 38000024, 2023). "We next compared the efficacy of TA99-HL2-KOA1 in synergy with TriVax (against Trp2, Gp100 and Tyrp1) in suppressing in vivo melanoma proliferation." (PMID 36911698, 2023). "Melanoma endogenously expresses Tyrp1 protein and can be killed in vitro by TRP1high and TRP1low effector CD8 T cells." (PMID 38000024, 2023).
melanoma (continued). "Although there were no clear objective radiographic responses to VSV-IFNβ-TYRP1, dose-dependent immunogenicity to TYRP1 and other melanoma antigens was seen." (PMID 38022659, 2023). "Zinc transporters ZNT5-6 and ZNT7 are essential for pigmentation and for the expression and function of tyrosinase-related protein TYRP1 in human melanoma cells and medaka fish." (PMID 37072620, 2023). "In this model, the therapeutic efficacy of the TA99 Ab, which specifically recognizes the Tyrp1 antigen expressed by B16 melanoma cells, has been shown to be dependent upon NK activity and ADCC." (PMID 35692755, 2022). "GILT is required for efficient MHC class II-restricted presentation of melanoma antigens, including tyrosinase and tyrosinase-related protein 1, by both APCs and melanoma cells." (PMID 35565329, 2022). "Whereas untreated lungs show melanoma covering nearly the entire lung surface, anti-Tyrp1-treated lung lobes exhibit relatively few, smaller nodules." (PMID 35454837, 2022). "We synthesized an amphiphilic nanoparticle (DSPE-PEG2000-peptide) by additive reaction of DSPE-PEG2000-NHS and peptide (two neoantigens of B16F10 melanoma cells: M20 and M27, with a highly-expressed peptide Tyrp1)." (PMID 35418151, 2022). "Transgenic mice overexpressing Grm5 (Tyrp1-Grm5) present with multiple melanoma located on the tail, with 100% penetrance and metastases, demonstrating that Grm5 drives melanoma initiation and progression." (PMID 35158973, 2022). "Accompanying the down regulation of pigmentation specific proteins such as tyrosinase and TYRP1, these biomarkers are highly specific for a type of highly invasive melanoma." (PMID 36776379, 2022). "It has been shown that Tyrp1 mRNA indirectly promotes melanoma cell proliferation by sequestering miR-16." (PMID 35076395, 2022). "Tyrosinase-related protein 1 (TYRP1) is the most abundant intracellular glycoprotein in melanoma and melanocytes." (PMID 36241983, 2022). "Proteins associated with pigmentation were identified in our targeted-proteomics analysis in melanoma cells, which included Ras-related protein Rab-7L1 (Rab29), L-dopachrome tautomerase (Dct), and 5,6-dihydroxyindole-2-carboxylic acid oxidase (Tyrp1)." (PMID 35745603, 2022). "For example, a treatment with cyclophosphamide together with an antibody targeting a native melanoma differentiation antigen, tyrosinase-related protein 1 (aTRP1), has been found to inhibit the growth of B16F10 melanoma tumors." (PMID 34691082, 2021). "In mouse melanoma model, immunization with human tyrosinase-related protein 1 (hTRP1) (or gp75) elicited antibody or cytotoxic T-cell responses to gp75 and immunized mice rejected metastatic melanomas and developed patchy depigmentation in their coats." (PMID 33156394, 2021). "Expression of tyrosinase, tyrosinase-related protein 1 (TRP-1) and tyrosinase-related protein 2 (TRP-2), and microphthalmia-associated transcription factor was inhibited in B16F10 melanoma cell lines." (PMID 33923988, 2021). "In melanoma cell lines, it was demonstrated that miR-155 induced TYRP1 mRNA decay and, in metastatic tissues, TYRP1 mRNA inversely correlated with miR-155 expression." (PMID 32185171, 2020). "Melanoma cell lines with the highest proliferation rate were among lines expressing TYRP1 transcript at a medium level, whereas those with the highest expression of TYRP1 at the transcript and protein levels exerted one of the lowest proliferation rates." (PMID 31624899, 2020). "This study assessed previously reported coding variants in albinism genes (TYR, OCA2, TYRP1, SLC45A2, SLC24A5, LRMDA) and common intronic, regulatory variants of OCA2 in individuals with amelanotic/hypomelanotic melanoma, pigmented melanoma cases and controls." (PMID 32966289, 2020). "TYRP1 mRNA levels in melanomas from patients who developed resistance to targeted therapeutics were examined using publicly available data sets." (PMID 31624899, 2020).